CUL4B (cullin 4B)
Description:
Core component of multiple cullin-RING-based E3 ubiquitin-protein ligase complexes which mediate the ubiquitination and subsequent proteasomal degradation of target proteins. The functional specificity of the E3 ubiquitin-protein ligase complex depends on the variable substrate recognition subunit. CUL4B may act within the complex as a scaffold protein, contributing to catalysis through positioning of the substrate and the ubiquitin-conjugating enzyme. Plays a role as part of the E3 ubiquitin-protein ligase complex in polyubiquitination of CDT1, histone H2A, histone H3 and histone H4 in response to radiation-induced DNA damage. Targeted to UV damaged chromatin by DDB2 and may be important for DNA repair and DNA replication. A number of DCX complexes (containing either TRPC4AP or DCAF12 as substrate-recognition component) are part of the DesCEND (destruction via C-end degrons) pathway, which recognizes a C-degron located at the extreme C terminus of target proteins, leading to their ubiquitination and degradation. The DCX(AMBRA1) complex is a master regulator of the transition from G1 to S cell phase by mediating ubiquitination of phosphorylated cyclin-D (CCND1, CCND2 and CCND3). The DCX(AMBRA1) complex also acts as a regulator of Cul5-RING (CRL5) E3 ubiquitin-protein ligase complexes by mediating ubiquitination and degradation of Elongin-C (ELOC) component of CRL5 complexes. Required for ubiquitination of cyclin E (CCNE1 or CCNE2), and consequently, normal G1 cell cycle progression. Regulates the mammalian target-of-rapamycin (mTOR) pathway involved in control of cell growth, size and metabolism. Specific CUL4B regulation of the mTORC1-mediated pathway is dependent upon 26S proteasome function and requires interaction between CUL4B and MLST8. With CUL4A, contributes to ribosome biogenesis.
Synonyms: CUL-4B; MRXHF2; MRXS15; MRXSC; SFM2
Tractability: Small molecule: a structure with a bound ligand is known. PROTAC: UniProt records ubiquitination sites on it; ubiquitination databases record sites on it; its protein half-life has been measured.
Gene: Protein-coding gene on chromosome X (120,505,920 to 120,604,074, reverse strand). Ensembl gene ENSG00000158290.
Subcellular location: Cytoplasm; Nucleus
Subcellular location (Human Protein Atlas): Nucleoplasm
Pathways (Reactome):
DNA Repair: DNA Damage Recognition in GG-NER; Dual Incision in GG-NER; Dual incision in TC-NER; Formation of Incision Complex in GG-NER; Formation of TC-NER Pre-Incision Complex; Gap-filling DNA repair synthesis and ligation in TC-NER; Recognition of DNA damage by PCNA-containing replication complex; Transcription-Coupled Nucleotide Excision Repair (TC-NER)
Metabolism of proteins: Neddylation
Gene Ontology:
Molecular function: damaged DNA binding; protein binding; ubiquitin ligase complex scaffold activity; ubiquitin protein ligase binding
Biological process: proteasomal protein catabolic process; proteasome-mediated ubiquitin-dependent protein catabolic process; protein ubiquitination; ribosome biogenesis; UV-damage excision repair; cell population proliferation; cellular response to UV; DNA damage response; epigenetic regulation of gene expression; G1/S transition of mitotic cell cycle; negative regulation of adipose tissue development; nucleotide-excision repair; regulation of apoptotic process; regulation of autophagy; regulation of cell cycle phase transition; regulation of cell population proliferation; regulation of cellular response to stress; regulation of DNA-templated DNA replication initiation; regulation of embryonic development; regulation of miRNA-mediated gene silencing; regulation of mitotic cytokinesis; regulation of natural killer cell activation; regulation of stem cell population maintenance; replication fork processing; spermatogenesis; and 4 more
Cellular component: Cul4-RING E3 ubiquitin ligase complex; Cul4A-RING E3 ubiquitin ligase complex; Cul4B-RING E3 ubiquitin ligase complex; extracellular exosome; nucleoplasm; nucleus; protein-containing complex; cytoplasm; cullin-RING ubiquitin ligase complex
Gene-disease validity (ClinGen):
ClinGen rates the evidence that CUL4B causes each of these diseases.
X-linked intellectual disability, Cabezas type (X-linked): Definitive.
Homologues: Orthologues: macaque CUL4B (99% identical), dog CUL4B (99% identical), rabbit CUL4B (99% identical), pig CUL4B (98% identical), guinea pig CUL4B (98% identical), chimpanzee CUL4B (98% identical), rat Cul4b (98% identical), mouse Cul4b (96% identical), tropical clawed frog cul4b (84% identical), zebrafish cul4b (83% identical), Caenorhabditis elegans cul-5 (22% identical), Drosophila melanogaster Cul5 (22% identical). Paralogues in human: CUL4A (70% identical), CUL3 (33% identical), CUL1 (26% identical), CUL5 (25% identical), CUL2 (24% identical), ANAPC2 (18% identical), CACUL1 (9% identical).
Diseases named in the same sentence as CUL4B in open-access papers:
CUL4B is named in the same sentence as 94 diseases in open-access papers, as found by Europe PMC text mining. Sharing a sentence is not in itself a finding about the gene and the disease. The quoted sentences say what the papers report.
breast carcinoma (14 papers, 2014 to 2025). "To determine the regulatory mechanisms of the CRL4B complex in breast cancer carcinogenesis, we analyzed proteins associated with CUL4B in human breast cancer adenocarcinoma MCF‐7 cells." (PMID 34026424, 2021). "We also found that high CUL4B expression was strongly correlated with poor prognosis in breast cancer patients." (PMID 34026424, 2021). "The results suggest that CUL4B lies at a critical crossroads between EMT and stem cell properties, supporting CUL4B as a potential novel target for the development of anti‐breast cancer therapy." (PMID 34026424, 2021). "To confirm the role of CUL4B in tumorigenesis, we collected 125 breast carcinoma samples from patients with breast cancer and performed tissue microarrays by immunohistochemical staining to examine the expression of CUL4B." (PMID 34026424, 2021). "Cullin4B (CUL4B) is identified as a master regulator in promoting breast cancer carcinogenesis, metastasis, and stemness." (PMID 34026424, 2021). "Strikingly, CUL4B expression is markedly upregulated during breast cancer progression and correlated with poor prognosis." (PMID 34026424, 2021). "The interaction of CUL4B with the Wnt and Notch signaling pathways, as well as its contribution to breast cancer progression, remains to be fully elucidated; thus, further research is necessary." (PMID 34026424, 2021). "CUL4A, which has the highest homolog with CUL4B, is overexpressed in primary breast cancers and hepatocellular carcinomas, and overexpression of CUL4A is associated with poor outcome in node-negative breast cancer." (PMID 25945838, 2015). "This hypothesis is supported by a recent study in breast cancer showing that CUL4B interacts with several HDAC-containing complexes and regulates EMT also in part via TGF-β regulation." (PMID 37686215, 2023). "We next investigated the possible role of CUL4B in breast cancer metastasis in vivo." (PMID 34026424, 2021). "Based on our observations that CUL4B was positively correlated with tumor malignancy, we investigated whether CUL4B affects stem‐like phenotypes in normal and breast cancer cells." (PMID 34026424, 2021). "Thus, HIF1α can directly activate CUL4B expression by binding to the hypoxia hormone response element (HRE) on the CUL4B promoter in breast cancer cells." (PMID 34026424, 2021). "Finally, to determine the clinicopathological relevance of our results, we analyzed the expression of CUL4B and its correlation with the clinical behaviors of patients with breast cancer." (PMID 34026424, 2021). "More importantly, our recent study demonstrated that the COPS5-associated protein CUL4B could interact with HDAC-containing complexes to promote EMT and stem cell production in breast cancer." (PMID 34993131, 2021). "Additionally, the CUL4B protein influences Tam-resistance of breast cancer cells by upregulating ER-α36 expression, which was mediated by downregulation of miR-32-5p." (PMID 34359587, 2021). "CUL4B has been shown to participate in the DNA damage repair pathway or in histone ubiquitination, and was found to be aberrantly expressed in a variety of cancers types, including breast cancer, and correlated with cancer progression and pathogenesis." (PMID 25883150, 2015). "We have demonstrated that CUL4B could upregulate the breast cancer stem cell population." (PMID 35534547, 2022). "In addition, analysis of METABRIC public datasets, obtained from cBioPortal, indicated that CUL4B expression levels were positively correlated with several molecular subtypes of breast cancer, including the Luminal, Her2, and Basal subtypes, while ERα expression showed the opposite trend." (PMID 34026424, 2021). "However, the role of CUL4B in the development of breast cancer remains poorly understood." (PMID 34026424, 2021). "Growth curve measurements indicated that CXXC5, CUL4B, or MTA1 stable knockdown reduced the growth ability of breast cancer cells and that CXXC5, CUL4B, or MTA1 overexpression enhanced the growth of MCF-7 cells." (PMID 36539038, 2023).
breast carcinoma (continued). "The expression of CXXC5, CUL4B, and MTA1 increased during the occurrence and development of breast cancer, and correspondingly, TSC1 expression decreased." (PMID 36539038, 2023). "We concluded that the PRMT6/PARP1/Cullin4B (CUL4B)‐Ring E3 ligase (CRL4B) complex transcriptionally represses PER3 and promotes breast cancer proliferation, invasion, and metastasis." (PMID 36941223, 2023). "We detected significantly upregulated expression of CXXC5, CUL4B, or MTA1 in breast carcinoma samples compared with that in normal tissues, and their expression levels increased with the histological grades of the tumor specimens." (PMID 36539038, 2023). "The chemotactic migration assay and cancer cell–bone matrix adhesion assay indicated that depletion of RUNX2, MTA1, or CUL4B hampered breast cancer cell metastasis to the bone, while overexpression of RUNX2, MTA1, or CUL4B resulted in the opposite trend." (PMID 35534547, 2022). "Thus, CUL4B could increase the early invasion ability of breast cancer cells." (PMID 34026424, 2021). "To further confirm this functional link, we investigated the influence of CUL4B, MTA1, Snail, and ZEB2 on the cellular behavior of breast cancer cells in vitro using transwell invasion assays." (PMID 34026424, 2021). "However, the role of CUL4B in breast cancer bone metastasis has not yet been explored." (PMID 35534547, 2022). "Analysis of online datasets further revealed augmented PRMT6, PARP1, CUL4B, and DDB1 levels in breast cancer tissues compared with normal tissues." (PMID 36941223, 2023). "The published breast cancer dataset (GSE48390) revealed a positive correlation between RUNX2, MTA1 and CUL4B, and negative correlations among RUNX2/MTA1/CUL4B and PPARα/SOD2." (PMID 35534547, 2022).
Intellectual disability (11 papers, 2012 to 2025). "Mutations in human CUL4B cause intellectual disability, and patients with CUL4B mutations manifest disruptions in skeletal development such as short stature and brachydactyly." (PMID 35784474, 2022). "Mutations in human CUL4B cause intellectual disability and patients with CUL4B mutations manifest disruptions in skeletal development such as a short stature and brachydactyly." (PMID 35784474, 2022). "Intellectual disability (ID), one of the most common human developmental disorders, can be caused by genetic mutations in Cullin 4B (Cul4B) and cereblon (CRBN)." (PMID 29370161, 2018). "CUL4B deficiency has been associated with intellectual disability, central obesity, muscle wasting, and dysmorphic features." (PMID 27900362, 2016). "Mutations in human CUL4B, one of the eight members in cullin family, are one of the major causes of X-linked mental retardation." (PMID 22606329, 2012). "In addition, human Cul4B is one of the most frequently mutated genes in X-linked mental retardation and cerebral malformations." (PMID 31170139, 2019). "Patients with variants in CUL4B exhibit syndromic intellectual disability (MIM #300354)." (PMID 31645981, 2019). "CUL4B is encoded on the X Chromosome, and deficiency in males is associated with intellectual disability, seizures, aggressive outbursts, central obesity, muscle wasting, short stature, macrocephaly, and dysmorphic features including brachydactyly, macroglossia, pes cavus, and prominent upper lip." (PMID 27900362, 2016). "Intellectual disability is a consistent feature associated with Cul4B-XLID, but the physiological function of Cul4B in neuronal cells or neurodevelopment remains to be determined." (PMID 22992378, 2012). "LoF is not the only mechanism associated with CUL4B-related intellectual disability, as shown by our patients with CUL4B duplication." (PMID 33530161, 2021).
osteosarcoma (11 papers, 2017 to 2025). A usually aggressive malignant bone-forming mesenchymal neoplasm, predominantly affecting adolescents and young adults. "This activation causes both CUL4B and NF‐κB subunits to become abundant in the nucleus of human osteosarcoma cells." (PMID 29377600, 2018). "To illuminate the underlying mechanisms of CUL4B overexpression in human osteosarcoma cells, we analyzed the promoter regions of the Cullin genes." (PMID 29377600, 2018). "Furthermore, CUL4B is involved in various immune-related cancers and inflammation, including pleural mesothelioma, human osteosarcoma, and colitis-associated cancer." (PMID 40230836, 2025). "To assess whether CUL4B overexpression is associated with osteosarcoma tumorigenesis, we collected 54 paired cancerous tissues and adjacent nontumor tissues." (PMID 29377600, 2018). "Given that RelA, RelB, and c‐Rel bind to the promoter region of CUL4B and regulate its expression, thereby causing CUL4B overexpression in osteosarcoma cells, we sought to determine whether the NF‐κB subunits were activated." (PMID 29377600, 2018). "Moreover, the increased expression of CUL4B in osteosarcoma patients was associated with larger tumor size (≥ 12 cm, P = 0.003) and higher MSTS stage (P = 0.0001)." (PMID 29377600, 2018). "Given that the TNF‐α/NF‐κB axis was activated in osteosarcoma cells, we next sought to investigate whether the overexpression of NF‐κB subunits in hFOB1.19 cells would cause CUL4B up‐regulation and p21 down‐regulation similar to that of osteosarcoma cells." (PMID 29377600, 2018). "A study found that in human osteosarcoma cells, CUL4B forms an E3 ligase with RBX1 (RING-box 1), DDB1 (DNA damage binding protein 1), and DCAF11 (DDB1 and CUL4 associated factor 11)." (PMID 39062505, 2024). "CUL4B, as a member of cullins, facilitates the assembly of E3 ligase complexes and is aberrantly expressed in many cancers, including osteosarcoma." (PMID 39062505, 2024). "For instance, the CUL4 analogue CUL4B is highly expressed in osteosarcoma cells, and its activity, upon NEDDylation by RING-Box 1 Protein (RBX1), allows for degradation of p21, causing cell cycle progression." (PMID 38534381, 2024). "Previous studies have demonstrated that CUL4B is related to chemoresistance in lymphoblastoid cells, non-small-cell lung cancer cells, osteosarcoma and bladder cancer cells." (PMID 33869025, 2021). "A study in osteosarcoma identified tumor-suppressor miR-300 as a negative regulator for CUL4B expression." (PMID 33233664, 2020). "The Cullin family has six classic members and two atypical members, and we determined why only CUL4B was overexpressed in osteosarcoma cells." (PMID 29377600, 2018). "CUL4B mRNA was significantly up‐regulated (~fourfold induction) in all four osteosarcoma cell lines compared to osteoblast cells." (PMID 29377600, 2018). "We observed osteosarcoma cells had increased RelA, RelB, c‐Rel, and CUL4B levels in the cytoplasm and nucleus compared to hFOB1.19 cells, but not p50 and p52." (PMID 29377600, 2018). "Inhibiting the TNF‐α/NF‐κB/CUL4B axis significantly inhibited osteosarcoma cell proliferation compared with control cells." (PMID 29377600, 2018). "Recently, we found that CUL4B was overexpressed in osteosarcoma and that the activated CUL4B formed an E3 ligase with DDB1, RBX1, and DCAF11, which further ubiquitinated p21 and caused p21 degradation, resulting in the disruption of cell cycle progression." (PMID 29377600, 2018). "In recent years, growing evidence indicates that CUL4B is highly expressed in several cancer types, such as esophageal cancer and osteosarcoma." (PMID 29377600, 2018). "In this study, we used four osteosarcoma cell lines and 54 osteosarcoma patients who were diagnosed at different MSTS stages and confirmed the specificity of CUL4B overexpression and its association with osteosarcoma tumorigenesis." (PMID 29377600, 2018).